STRADB (STE20 related adaptor beta)
Description:
Pseudokinase which, in complex with CAB39/MO25 (CAB39/MO25alpha or CAB39L/MO25beta), binds to and activates STK11/LKB1. Adopts a closed conformation typical of active protein kinases and binds STK11/LKB1 as a pseudosubstrate, promoting conformational change of STK11/LKB1 in an active conformation (By similarity).
Synonyms: ALS2CR2; ILPIP; PRO1038; STLK6; CALS-21; PAPK; ILPIPA
Tractability: No criterion of Open Targets' tractability assessment is met for any kind of drug.
Gene: Protein-coding gene on chromosome 2 (201,387,858 to 201,480,850, forward strand). Ensembl gene ENSG00000082146.
Subcellular location: Nucleus; Cytoplasm
Subcellular location (Human Protein Atlas): Cytosol; Nucleoplasm; Primary cilium; Primary cilium tip
Pathways (Reactome):
Signal Transduction: Energy dependent regulation of mTOR by LKB1-AMPK
Gene Ontology:
Molecular function: protein binding; protein kinase activity; protein serine/threonine kinase activator activity; ATP binding
Biological process: activation of protein kinase activity; protein export from nucleus; protein phosphorylation
Cellular component: cytoplasm; cytosol; nucleoplasm; nucleus; serine/threonine protein kinase complex
Genetic constraint (gnomAD): Loss-of-function variants: 27 observed, 47.01 expected, observed/expected ratio (o/e) 0.57, 90% interval 0.42 to 0.79. The synonymous counts are far from expectation, so gnomAD's model fits this gene poorly and the ratio says little. Missense variants: 313 observed, 446.32 expected, observed/expected ratio (o/e) 0.7, 90% interval 0.64 to 0.77. Synonymous variants: 125 observed, 163.03 expected, observed/expected ratio (o/e) 0.77, 90% interval 0.66 to 0.89.
Homologues: Orthologues: macaque STRADB (99% identical), chimpanzee STRADB (98% identical), dog STRADB (93% identical), rabbit STRADB (92% identical), mouse Stradb (91% identical), rat Stradb (90% identical), guinea pig STRADB (88% identical), pig STRADB (86% identical), tropical clawed frog stradb (59% identical), zebrafish STRADB (51% identical). Paralogues in human: STRADA (43% identical), OXSR1 (26% identical), MAP4K4 (26% identical), TNIK (26% identical), STK39 (25% identical), STK25 (25% identical), MINK1 (24% identical), STK24 (24% identical), STK26 (24% identical), MAP4K3 (24% identical), MAP4K5 (24% identical), MAP4K1 (23% identical), and 23 more.
Diseases named in the same sentence as STRADB in open-access papers:
STRADB is named in the same sentence as 7 diseases in open-access papers, as found by Europe PMC text mining. Sharing a sentence is not in itself a finding about the gene and the disease. The quoted sentences say what the papers report.
tumor (3 papers, 2022 to 2024). "STRADB, on the other hand, regulates LKB1 kinase, which has been shown to synergize with PTEN to exert its tumor-suppressive role in several cancer entities." (PMID 35459737, 2022).
STRADB also shares sentences with these, for which no sentence is quoted: cancer (1 paper); colon tumor (1); infection (1); lateral sclerosis (1); melanoma (1); triple-negative breast carcinoma (1).